IRF3 (interferon regulatory factor 3)
Diseases named in the same sentence as IRF3 in open-access papers (continued):
Sharing a sentence is not in itself a finding about the gene and the disease.
infection (continued). "Because the MAVS and IRF3 KOs had a clear effect on the expression of ISGs after intracellular poly I:C stimulation, we investigated whether a similar effect could be observed after SAV3 infection." (PMID 37588594, 2023). "Furthermore, infection with TBEV activates innate immune signaling by engaging with the pattern recognition receptor RIG-I/MDA5, leading to the translocation of the interferon regulatory factor 3 (IRF-3) to the nucleus." (PMID 37512806, 2023). "Moreover, knockdown of DNMT1 promoted the transcription of IRF3 in cells either with or without VSVΔ51 infection." (PMID 37880243, 2023). "Infections with the highly attenuated Modified Vaccinia virus Ankara (MVA) served as a positive control for the activation of the IRF3 pathway; MVA is a natural VACV mutant with many inactivated viral genes, including B2R, and is known to efficiently activate IRF3." (PMID 37016144, 2023). "IRF3 is ubiquitinated during infection with the Sendai virus, which inhibits the interaction between IRF3 and peptidyl-prolyl cis-trans-isomerase NIMA interacting 1, thereby preventing the ubiquitination and subsequent degradation of IRF3 and enhancing the host’s immune response." (PMID 37256060, 2023). "VACV∆C7L infection of lung AECIIs induced phosphorylation of IRF3 while WT VACV failed to induce." (PMID 35351885, 2022). "We could detect low levels of CXCL10 in supernatants from IRF3‐KO cells, but there was no increase above baseline after infection." (PMID 35670106, 2022). "Moreover, NSP5 and N suppressed IFN expression induced by infection of Sendai virus or transfection of a synthetic mimic of dsRNA, poly (I:C), inhibiting TBK1 and IRF3 phosphorylation, and restraining the nuclear translocalization of IRF3." (PMID 35075101, 2022). "Moreover, their assembly is required for IRF3-mediated production, and the absence of avSGs sensitized the cells to infection." (PMID 35098996, 2022). "Furthermore, compared with wild-type ASFV, infection of ASFVΔI267L increased RIG-I ubiquitination, enhanced RIG-I-VISA interaction, and induced higher levels of IRF3 phosphorylation, suggesting that deletion of I267L attenuates the ability of ASFV to antagonize RIG-I-mediated signaling." (PMID 35089988, 2022). "Notably, IRF3 expression was not upregulated following infection, likely because it is activated via phosphorylation and subsequent dimerization." (PMID 36268025, 2022). "However, the export of IRF3 is dominant, resulting in a greater pool of IRF3 localized to the cytoplasm in the absence of infection." (PMID 33805458, 2021). "At later time points post-infection (19 h), minimal to no IRF3 expression was observed." (PMID 33419081, 2021). "Initially, cGAS was described as a cGAMP synthase required for IRF3 dimerization following infection of murine fibroblast cells with herpes simplex virus type-1 (HSV-1), a DNA herpesvirus previously known to induce the expression of IFNs through the STING-IRF3 axis." (PMID 33708225, 2021). "Moreover, the protein levels of phosphorylated TBK1 (p-TBK1), p-IRF3, and p-p65 were analyzed to determine whether SAFA was indeed involved in the activation of type I IFN and inflammatory responses under SFTSV infection." (PMID 34788350, 2021). "Moreover, the use of the mTOR inhibitor Ku-0063794 or the mTORC1 inhibitor rapamycin did not affect the ability of IRF3 to accumulate into the nuclear compartment following the infection of primary fibroblasts with SeV." (PMID 33411856, 2021). "The homologs of STING in invertebrate are postulated to loss the function to induce innate immune response against infection for the lack of a carboxy-terminal tail (CTT) domain which is the essential domain for mammalian STING to recruit the critical downstream TBK1 and IRF3 signaling components." (PMID 34168656, 2021). "Infection with SARS-CoV failed to induce detectable phosphorylation of IRF3 in infected cells." (PMID 34378952, 2021).
infection (continued). "To evaluate whether infection with candidate oncolytic VACV (WR/TK−/Δ, WR/TK−/2Δ, and WR/TK−/3Δ) leads to activation of the IRF3 pathway, we determined the amounts of phosphorylated IRF3 (p-IRF3) by western blot after infection of human cancer cells." (PMID 34553028, 2021). "Interestingly, after virus stimulation, IRF3a is degraded slower than phosphorylated IRF3 and so the ratio of negative versus positive modulator increases with ongoing infection, potentially contributing to a downregulation of the type I IFN response." (PMID 32645843, 2020). "The time needed for virus antigen expression and IRF3 phosphorylation may differ and not all infected cells were at the same stage of infection." (PMID 31817126, 2019). "However, the IFI16-dependent STING pathway can only induce IRF3 but not NF-κB activation, which would serve to preserve the survival activities regardless of the antiviral response during infection." (PMID 28596706, 2017). "The use of a different, less efficient Ad internalization route in BMMs may be responsible for the lack of detectability of NF-κB and IRF-3 activation upon infection and therefore for a very weak cytokine response." (PMID 28765216, 2017). "MDP treatment following infection with HSV1 (MOI 0.1) showed no further induction of IRF3 or NF-κB." (PMID 26830977, 2016). "Thus, it can be concluded that HBV is well replicable in the IFNAR−/− and IRF3/7−/− hepatocytes and essentially no IFNs are principally produced in these hepatocytes during the infection." (PMID 27626689, 2016). "Since IRF3 is required for the induction of IFNβ, we asked whether its activation was impaired during infection of cells lacking PKR." (PMID 26939124, 2016). "Thus, we have next evaluated whether treatment of IAV-infected mice with LTB4 may have consequences on IRF3, IRF7 and NF-κB activation following infection." (PMID 26444420, 2015). "IRF-7, together with IRF-3, is known to play a pivotal role in the induction of IFN-α and IFN-β genes through binding with PRDI in cells infected with virus, although it was suggested that IRF-7, rather than IRF-3, is important to suppress the infection and replication of HCV in the cells." (PMID 24587086, 2014). "Strikingly, IRF3 activation could not be detected following infection with any of our panel of influenza viruses (Ud, Ud-Δ99, WSN, PR8, and PR8-ΔNS1) in the presence of ActD." (PMID 24478437, 2014). "Indeed, we observed that IRF3 activation and IFN-β production were also drastically enhanced in PMLIV-overexpressing cells following transfection with poly(I:C) or infection with viruses from different families such as SeV, EMCV, HTLV-1, influenza virus or vaccinia virus." (PMID 24586174, 2014). "Moreover, it has been found that during infection with RNA viruses a BH3-like domain of IRF-3 mediates binding to cytosolic Bax (but not Bcl-2, Bcl-XL or Bak) to induce Bax activation, culminating in cytochrome c release and apoptosome formation." (PMID 22935147, 2012). "To determine whether IRF-3 was responsible for synthesis of type I IFN during Y. pestis infection, we challenged wild type, Irf3−/− and Irf7−/− mice with Y. pestis KIM D27 and measured gene expression in the lungs on days 2 and 4 post-infection." (PMID 22911267, 2012). "IRF3 activation could be detected in untreated cells infected with our vM0 preparations of PIV5-VΔC and SeV, but, in contrast to infections with DI-rich preparations of these viruses, treatment with CHX had an inhibitory effect on IRF3 activation in infected cells." (PMID 22049094, 2012). "Infection with RNA viruses or transient transfection with dsRNA can directly and rapidly induce early ISGs, such as ISG15, through IRF3, after activation of the RIG-I/MAVS pathway and recruitment of TRAF3, an essential adapter which recruits the downstream IRF3 kinases TBK1/IKKε." (PMID 22022264, 2011). "Indeed, infections with HSV-1 and hCMV rapidly activate IRF3 following virus binding and entry." (PMID 21347389, 2011).
infection (continued). "Since IRF3 is able to form homodimers in response to VZV infection when the viral kinase ORF47p is not expressed, we wondered whether infection with the mutant VZV ROka47S leads to an increase of IRF3-dependent gene expression compared to the WT VZV infection." (PMID 21347389, 2011). "However, disruption of IFN-β-signalling failed to inhibit IRF-3 translocation to the nucleus in response to MVA infection in HeLa cells (transfected with siRNA against IFNAR) or macrophages (from IFNAR-deficient mice)." (PMID 21698224, 2011). "Interestingly, we found SLPs to activate NFκB but not IRF3, downstream of TLR4 which correlated with the observation that TRIF−/− mice did not have increased susceptibility or severity of infection." (PMID 21738466, 2011). "Interestingly, the early activation of IRF3 observed with WT HSV-1 was not seen following infection with D8, likely owing to the early and exclusive cytoplasmic localization of ICP0 from this mutant." (PMID 20454685, 2010). "It is worthy to point out that our result does not exclude the antiviral activity of the IRF-IFN pathway in γHV68 lytic replication, although deficiency of IRF3 and IRF7 or IFNAR did not appear to impact the initiation of γHV68 lytic infection as assessed by plaque assays." (PMID 20686657, 2010). "It has been shown that at early hours of HCV infection, the hepatocytes were able to relocalize IRF-3 from the cytoplasm to the nucleus; however, once cleavage of IPS-1 by NS3/4A occurs, which usually can be detected 24 hours after infection, none of the cells were found with nuclear IRF-3." (PMID 21274284, 2010). "In order to study the involvement of RIGI in antiviral response stimulation via activation of IRF3/NFκB, we expressed RIGI (FLAG tagged) in 293 cells (these cells does not express majority of endogenous PRRs) and analyzed IFN/NFκB activation following HPIV3 infection." (PMID 19922606, 2009). "SeV induced a specific DNA binding activity 12- and 24 h after infection only in IKKγ-WT expressing cells; no DNA binding activity was seen in IKKγΔ expressing cells (this band was previously shown to be DNA sequence specific and contain IRF3)." (PMID 19956647, 2009). "This partial dependence on Irf3 was not changed by varying the multiplicity of infection." (PMID 19578435, 2009). "Therefore, we performed a chromatin immunoprecipitation (ChIP) assay to determine whether MV infection of pHMs induced IRF3 and IRF7 binding to the IRF7 ISRE and IRFE at 12 h after infection, as IRF7 first became markedly upregulated at this time point." (PMID 18617992, 2008). "Thus, in cortical neurons, the intracellular viral RNA sensors RIG-I and MDA5 are absent when WNV enters the cytoplasm but are induced after infection through an IRF-3-dependent mechanism." (PMID 17676997, 2007). "Since both IRF3 and SVCV-P drive TBK1 phase separation, with IRF3 facilitating IFN production and SVCV-P inhibiting it by disrupting IRF3-TBK1 phase separation, we hypothesized that during SVCV infection, IRF3-TBK1 and SVCV-P-TBK1 droplets might interact and remodel into a new phase-separated state." (PMID 41363845, 2026). "This aligns with higher cellular CXCL10 mRNA expression in LNCaP cells compared to PANC-1 upon rSFV infection, supporting the hypothesis that innate non-conventional cellular pathways, such as NF-kB or IRF3 activation, play a role in SFV-induced CXCL10 expression independent of the JAK-STAT pathway." (PMID 38425844, 2024). "As infection proceeded, the intensity of the IRF3 signal in the puncta increased as the level of cytoplasmic-dispersed IRF3 decreased, indicating that the total amount of IRF3 in the cells did not dramatically change during infection and that only its subcellular localization changed." (PMID 38285487, 2024).
infection (continued). "We also observed that PRRSV-ADE infection visibly cut down the transcripts of IRF-3, IRF-7, and NF-κB in PAMs in the early stage of infection (after 12–24 h infection), implying that disruption of these three transcription factors may play a crucial part in PRRSV-ADE infection." (PMID 37008366, 2023). "Importantly, we observed that while L. donovani induces the accumulation of IRF3 in the nuclear fraction of macrophages at 6 h and 24 h post-infection, this does not occur upon infection with L. donovani:ISP2, linking a serine peptidase activity-dependent pathway to IRF3-related IFN-I response." (PMID 35154115, 2022). "To test whether the nucleic acid-sensing pathways have a function in host defense against VACV∆C7L infection, we performed intranasal infection of VACV∆C7L in cGas−/−, Sting1gt/gt (which lack functional STING), Ifih1−/− (MDA5 knockout), Ifih1−/−Sting1gt/gt or Irf3−/− mice." (PMID 35351885, 2022). "However, we could not detect activation of these pathways even by 3 days after BKPyV infection: IRF3 remains unphosphorylated and cytoplasmic, and no ISGs were induced." (PMID 31142673, 2019). "Notably, much higher levels of phosphorylation of Tbk1 and Irf3 were stimulated by ISD and 2′3′-cGAMP than by the ECTV infection, indicating that ECTV might express some potent immunomodulators that are involved in the modulation of TBK1 and IRF3 phosphorylation." (PMID 29963044, 2018). "Interestingly, we saw only a moderate induction of the IRF3 gene early during infection and the levels remained consistent throughout infection; however, there were no changes in the transcription of any of these genes after the addition of either IFN-β neutralizing antibody or IgG control." (PMID 25798928, 2015). "Notably, IRF3 5A was not degraded by TRIM26 even under the condition of infection with SeV and VSV." (PMID 25763818, 2015). "Thus, by blocking the translation of host mRNAs that are transcribed, for instance, following activation of NF-κB, IRF-3 or the JAK/STAT signaling pathways, there is a decreased production of many inflammatory mediators and consequential reduced recruitment of leukocytes to the site of infection." (PMID 26334635, 2015). "Interestingly, the cytokines whose levels were increased in HMA+ strains during mBMDM infection in vitro and in PECS ex vivo, including IL6, CCL5, and IL10, are not those that would be expected to change based on interference with known mitochondrial signaling pathways (i.e., MAVS, NF-kB, IRF3/7)." (PMID 24781109, 2014). "Therefore, since TLR3 and TLR4 molecules contribute to the generation of a normal IFN response through activation of IRF-3, IRF-5, and IRF-7 after infection with neurotrophic virus, we tested whether the ablation of TLR3 and TLR4 molecules affected type I innate responses in JEV infection." (PMID 25188232, 2014). "In THP1 cells, physalin F inhibited SeV-induced phosphorylation of IRF3, STAT1, and STAT2 at 4 h post-infection, and had no marked effects on it at 8 h post-infection." (PMID 41599057, 2026). "As expected, increased levels of phosphorylation of IRF3 and STAT1 were found in AGO2 knockout cells after infection with DelNS1 WSN virus, regardless of the presence of DROSHA." (PMID 40949099, 2025). "Infection with the SIRV strain rSC0163 resulted in increased protein expression of cGAS, p-STING, p-TBK1, and p-IRF3 compared with infection by the non-SIRV strain rSC0162." (PMID 40876118, 2025). "We repeated this analysis using the virus only conditions and found that IRF5, but not IRF3 or IRF7, was significantly upregulated in HIV-1–infected MDMs isolated from older donors despite similar levels of infection in vitro." (PMID 40493408, 2025). "As shown by the infection of specific-pathogen-free pigs with wild-type and ΔNpro mutant CSFV strains, the Npro-induced impairment of the IRF3-dependent IFN pathway is not a major factor for pestiviral virulence." (PMID 39861896, 2025).
infection (continued). "HSV-1-and L. monocytogenes-infection induced S-nitrosylation of endogenous STING in PMs, but not cGAS, IRF3 or TBK1." (PMID 38409248, 2024). "IRF3, unlike IFR7, is degraded rapidly after infection without being newly reproduced, and like IRF7, the lack of IRF3 can negatively affect the immune response due to the lack of induction of IFN-α/β." (PMID 38932312, 2024). "Infection of cpdm MEFs, lacking SHARPIN expression, with SeV resulted in a slight reduction in NF-κB-dependent genes, but increased IRF3-dependent transcription." (PMID 38001254, 2024). "In striking contrast, IRF3 KD had an initial effect on the type III IFN, IFNL1 after 10 h of infection, but did not affect its later expression at 24 h." (PMID 37564646, 2023). "In contrast, IRF3 and IRF7-1/3 KOs showed no elevated levels of these genes after infection, and, for the MAVS KO, induction was reduced compared to Wt." (PMID 37588594, 2023). "SAV3 infection in control and IRF7-1 KO cells yielded similar titers and no cytopathic effect, while IRF3 and MAVS KOs presented with severe cytopathic effect and increased titers 6 days after SAV 3 infection." (PMID 37588594, 2023). "Infection of HFFs with MVA resulted in STING and IRF3 phosphorylation that was markedly reduced in the absence of DNA-PKcs, indicating that DNA-PKcs is required for vaccinia virus-driven activation of the STING/TBK1/IRF3 signaling axis." (PMID 38269102, 2023). "Consistent with earlier findings, IRF3 mRNA was not induced after 10 h of RSV infection and only increased by 1.7 ± 0.7-fold increase after 24 h of infection." (PMID 37564646, 2023). "While we did not observe differences in IFNAR1, IRF3, STAT1, nor ISG15 expression induced by the two strains, IFNβ, LPG2, RIG1, and OAS1 were significantly induced after infection with Mb3601, but not H37Rv." (PMID 34307535, 2021). "This is a clever, multifaceted approach to ensure IRF3 is not activated downstream, which likely allows HCMV to continue its infection cycle while dampening an important host antiviral response." (PMID 34440891, 2021). "Unlike IRF3, IRF7 is not expressed ubiquitously in cells; instead, its expression is induced upon pathogen infection or stimulation." (PMID 34782737, 2021). "Although able to improve antitumor immune responses, levels of p-IRF3 and IFN-β mRNA detected after infection with WR/TK−/3Δ do not reach the levels observed after infection with MVA." (PMID 34553028, 2021). "The expression of MDA5, TANK and P-IRF3 protein decreased significantly (P < 0.01) after HEK-293 T cells infection with EMCV while the expression of MAVS and IRF3 protein showed no significant change." (PMID 34587973, 2021). "Western Blot analysis revealed cleavage of TBK1, but not of MAVS or IRF3, during wt FMDV-A12 infection." (PMID 32667958, 2020). "Knockout experiments in mice have shown that lack of IRF3 delays the immune response, while cells lacking IRF7 respond early but are unable to fend off the infection without the signal amplification." (PMID 32645843, 2020). "During infection with wildtype L2 virions, we did not detect activation of STING of IRF3, suggesting that linear DNA is also shielded." (PMID 33253291, 2020). "M. avium infection induced IRF3 and IRF7 nuclear translocation in WT but not Mavs–/–BMMs at 24 hr post-infection." (PMID 32463840, 2020). "Infection with NH/P68, but not with Armenia/07, induces phosphorylation of STING and IRF3 at 16 hpi, indicating that the STING pathway is activated in response to the infection with the attenuated, but not with the virulent, ASFV strain." (PMID 30918080, 2019). "In contrast, NH/P68 infection induces activation of the cGAS-STING route in the presence and absence of AraC, since phosphorylation of both STING and IRF3 are observed." (PMID 30918080, 2019). "A previous study demonstrated that transfection of EV-A71-derived RNA, but not EV-A71 infection, induces phosphorylation of an IFN-β transcriptional factor IRF3 in HeLa cells." (PMID 31787104, 2019).